MIRLET7BHG (MIRLET7B and MIRLET7A3 host gene)
Synonyms: linc-Ppara; PRR34-AS1
Gene: Long non-coding RNA gene on chromosome 22 (46,044,913 to 46,116,382, forward strand). Ensembl gene ENSG00000197182.
Gene Ontology:
Biological process: miRNA-mediated post-transcriptional gene silencing
Cellular component: RISC complex
Diseases named in the same sentence as MIRLET7BHG in open-access papers:
MIRLET7BHG is named in the same sentence as 1 disease in open-access papers, as found by Europe PMC text mining. Sharing a sentence is not in itself a finding about the gene and the disease. The quoted sentences say what the papers report.
glioma (1 paper, 2024). A benign or malignant brain and spinal cord tumor that arises from glial cells (astrocytes, oligodendrocytes, ependymal cells). "In a study of glioma patients, researchers investigated whether MIRLET7BHG regulates glioma progression by up-regulating GSDMs." (PMID 39641053, 2024).